TCP11X1 (t-complex 11 family, X-linked 1)
Tractability: No criterion of Open Targets' tractability assessment is met for any kind of drug.
Gene: Protein-coding gene on chromosome X (102,215,298 to 102,229,532, forward strand). Ensembl gene ENSG00000268235.
Gene Ontology:
Biological process: regulation of sperm capacitation; signal transduction
Cellular component: acrosomal vesicle; sperm flagellum
Homologues: Orthologues: chimpanzee TCP11X2 (70% identical), rat Tcp11x2 (69% identical), mouse Tcp11x2 (63% identical), Caenorhabditis elegans M05D6.2 (25% identical), Drosophila melanogaster CG16721 (25% identical). Paralogues in human: TCP11X2 (99% identical), TCP11 (69% identical), TCP11L1 (37% identical), TCP11L2 (35% identical).